PTK7 (protein tyrosine kinase 7 (inactive))
Diseases named in the same sentence as PTK7 in open-access papers (continued):
Sharing a sentence is not in itself a finding about the gene and the disease.
gastric cancer (9 papers, 2010 to 2025). A primary or metastatic malignant neoplasm involving the stomach. "In conclusion, the observation that PTK-7 status is independently associated with survival in gastric cancer patients supports the importance of it as a determinant of gastric tumor behavior." (PMID 31820857, 2020). "Early studies examined Ptk7 expression in a variety of cancers, and revealed that Ptk7 levels are higher in lung, colon and gastric cancers and are associated with poor prognosis and higher metastatic potential." (PMID 27438854, 2016). "In gastric cancer, PTK7 expression was found to be associated with tumor differentiation as well." (PMID 39474113, 2024). "PTK7 is highly expressed in colon cancer, lung cancer, gastric cancer, and intrahepatic cholangiocarcinoma, and is considered a potentially important prognostic marker." (PMID 35257502, 2022). "High PTK7 expression has been found in various cancers, including gastric cancer and intrahepatic cholangiocarcinoma." (PMID 35257502, 2022). "It would be useful to include the expression of PTK-7 in models predicting gastric cancer survival and to use the current clinicopathological system as a general guide in conjunction with the molecular stratification when treatment decisions are made." (PMID 31820857, 2020). "In the present study, we aimed to investigate the impact of PTK-7 expression on gastric cancer outcomes to determine its potential role as a therapeutic target." (PMID 31820857, 2020). "The method reported a LOD of 2.15 × 106 particles/μL using MUC1 probe for gastric cancer cell line HGC-27-derived EV sample, as well as validation for other gastric cancer biomarkers (EpCAM, PTK7, PD-L1) for both cell line EV isolates and human plasma specimens." (PMID 41404198, 2025). "We sought to determine the potential impact of PTK-7 expression levels, on gastric cancer outcomes." (PMID 31820857, 2020). "PTK-7 serves as a modulator of better survival in gastric cancer." (PMID 31820857, 2020). "Additional oncogenic pathways are possibly involved in PTK-7 regulation in gastric cancer." (PMID 31820857, 2020). "In gastric cancer, although studies have shown that PTK7 is overexpressed, both studies confirmed that its expression is associated with better OS and disease-free survival (DFS), which suggests that PTK7 may be a double-edged sword in gastric cancer treatment." (PMID 39474113, 2024). "Studies on PTK7 in gastric cancer (GC) were reported in the early 21st century." (PMID 39474113, 2024). "For instance, agents against some overexpressed targets such as CD71, PTK7, CD74 and SLC44A4 could be evaluated in some conditions such as breast, colon and gastric cancer." (PMID 37740463, 2023). "We also identified that ADCs against CD71, PTK7, CD74, SLC44A4 and LIV‐1 were not under evaluation in breast, colorectal, prostate and gastric cancer, which suggests potential opportunities for evaluation." (PMID 37740463, 2023).
T-cell acute lymphoblastic leukemia (9 papers, 2014 to 2023). Acute lymphoblastic leukemia of T-cell origin. "Protein tyrosine kinase 7 (PTK7) is over-expressed in approximately 70% of T cell acute lymphocytic leukemia (T-ALL)." (PMID 26863567, 2016). "Similarly, the use of aptamers showed that the protein tyrosine kinase 7 (PTK7) is enriched in T-cell acute lymphoblastic leukemia, and the immunoglobin heavy chain mu in Burkitt’s lymphoma." (PMID 27104834, 2016). "The DNA aptamer sgc8c, which possesses strong affinity for protein tyrosine kinase 7 (PTK7), abundantly expressed on the surface of CCRF-CEM (T-cell acute lymphoblastic leukemia) cells, was assembled onto the surface of Au NPs." (PMID 25295268, 2014).
lymph node metastasis (8 papers, 2014 to 2024). "Another investigation of PTK7 expression in 79 consecutive invasive breast cancer tissues by immunohistochemistry found that PTK7 expression level negatively associates with tumor grade and lymph node metastasis." (PMID 34367983, 2021). "Elevated PTK7 expression was significantly associated with lymph node metastases, seminal vesicle invasion, prostate cancer stage, the higher preoperative prostate-specific antigen, the higher Gleason score, angiolymphatic invasion, and biochemical recurrence." (PMID 24987951, 2014). "PTK7 overexpression in prostate cancer patients can predict lymph node metastasis, poor overall survival, and recurrence-free survival." (PMID 36293051, 2022). "The present data provide evidence that PTK7 predicts lymph node metastasis and poor overall survival and biochemical recurrence-free survival, highlighting its potential function as a therapeutic target for prostate cancer." (PMID 24987951, 2014). "In prostate cancer, higher PTK7 expression means more lymph node metastasis, later tumor stage, higher frequency of seminal vesicle invasion and angiolymphatic invasion, higher levels of preoperative PSA, higher risk of biochemical recurrence, and higher Gleason score." (PMID 39474113, 2024). "The authors reported that negative PTK-7 expression was associated with poor differentiation, lymph node metastasis, and advanced TNM stage." (PMID 31820857, 2020). "In another study examining PTK-7 expression in both primary breast tumors and their lymph node metastases, expression positivity in lymph node metastasis was significantly associated with shorter DFS." (PMID 31820857, 2020). "Moreover, elevated PTK7 was observed in TNBC with lymph node metastasis." (PMID 34367983, 2021).
melanoma (8 papers, 2014 to 2026). A malignant, usually aggressive tumor composed of atypical, neoplastic melanocytes. "PTK7, another melanoma-associated target, was exploited by engineering a hybrid vesicle composed of cationic lipid and mesenchymal stem cell membranes, electrostatically coated with the Sgc8-c aptamer." (PMID 41560835, 2026). "A late 20th-century study found that PTK7 mRNA expression was detected in only 54% of melanoma cell lines and 20% of melanoma biopsies." (PMID 39474113, 2024). "Regarding the role played by PTK7 in melanoma, it has been shown that PTK7 is regulated by AMIGO2, and the two work together to promote tumor cell survival." (PMID 39474113, 2024). "In lymphoma and melanoma, PTK7-targeting aptamer-fluorescent and -radiolabelled probes have shown potential as high-quality molecular imaging agents." (PMID 39474113, 2024). "These methodologies applied here allowed us to detect differences in the expression of the tumor marker PTK7 in two different melanoma tumor models." (PMID 34620894, 2021). "The pseudokinase PTK7 was originally identified as a protein overexpressed in several cancer cell lines, including melanoma and colon." (PMID 24409301, 2014). "Key aptamer targets in melanoma include PD-L1, nucleolin, and PTK7." (PMID 41560835, 2026). "PTK7 is regulated by AMIGO2 to promote melanoma cell survival." (PMID 39474113, 2024). "As can be seen, the expression of PTK7 in melanoma is still unclear, and its expression level may show significant changes with disease progression." (PMID 39474113, 2024). "However, a recent study found that PTK7 expression was upregulated 67-fold in the metastatic murine B16-F10 melanoma cells compared to the murine melanoma B16-F1 cells." (PMID 39474113, 2024). "Therefore, PTK7 may act more as an oncogene in melanoma, but whether and when PTK7 has cancer-inhibitory effects needs to be progressively explored in subsequent studies." (PMID 39474113, 2024). "Moreover, the sensitive and effective detection of PTK7 may represent a good strategy in the early diagnosis of melanoma." (PMID 34620894, 2021). "Finally, overexpression of PTK7 in a PTK7-negative model of melanoma was associated with an increased number of metastases." (PMID 25962058, 2015). "Likewise, it also delves into another non-metastatic melanoma model, in order to optimize biological control methods, both biodistribution and imaging, achieving a sensitive and effective detection of PTK7 with these probes." (PMID 34620894, 2021). "In the absence of any available PTK7-negative human CRC cells, we used a B16F10 melanoma cell line, a PTK7-negative cell with well documented ability to produce lung metastases in xenograft models, as a model." (PMID 25962058, 2015).
hepatocellular carcinoma (7 papers, 2021 to 2024). A malignant tumor that arises from hepatocytes. "In hepatocellular carcinoma (HCC), it was first shown that PTK7 is downregulated and that the mechanism of PTK7 silencing is associated with promoter hypermethylation." (PMID 39474113, 2024). "These targets are erythropoietin-producing hepatocellular carcinoma A2 (EphA2), tissue factor (TF), and protein tyrosine kinase 7 (PTK7)." (PMID 37998743, 2023). "Potential new targets such as erythropoietin-producing hepatocellular carcinoma A2 (EphA2), tissue factor (TF), and protein tyrosine kinase 7 (PTK7) are currently under study in clinical trials." (PMID 37998743, 2023). "Here, we have alreadydemonstrated the delivery of a protein and a fluorophore specificallyto PTK7-positive lymphoma and hepatoma cells." (PMID 37473438, 2023). "Potential new targets such as erythropoietin-producing hepatocellular carcinoma A2 (EphA2), tissue factor (TF), and protein tyrosine kinase 7 (PTK7) are currently under investigation in clinical trials." (PMID 37998743, 2023). "A bioinformatics analysis reported that PTK7 is highly expressed in stage I-IV hepatocellular carcinoma (HCC) and considered as an independent prognostic marker for reduced overall survival." (PMID 34367983, 2021).
prostate carcinoma (7 papers, 2014 to 2024). A carcinoma that arises from epithelial cells of the prostate gland. "In prostate cancer, PTK7 protein can act as an independent risk factor for OS and RFS." (PMID 39474113, 2024). "Compared with benign prostatic hyperplasia tissues, PTK7 expression was upregulated in prostate cancer tissues." (PMID 39474113, 2024). "In contrast, FZD4 and PTK7 levels were similar (low and high, respectively) in prostate and prostate cancer." (PMID 29717114, 2018). "We evaluated PTK7 expression in prostate cancer and its prognostic and predictive significances in this study." (PMID 24987951, 2014). "This study is aimed to investigate the prognostic and predictive significance of PTK7 in patients with prostate cancer." (PMID 24987951, 2014). "The results revealed that the overexpression of PTK7 in prostate cancer was an independent prognostic factor for poor overall survival and biochemical recurrence-free survival." (PMID 24987951, 2014). "Then, we examined the immunohistochemical expression of PTK7 in 180 prostate cancer specimens and evaluated its clinical significances." (PMID 24987951, 2014). "The data showed the crucial role of PTK7 as a prognostic and lymph node metastasis biomarker as well as a novel potential therapeutic target in prostate cancer." (PMID 24987951, 2014). "PTK7 is expressed at higher levels in aggressive prostate cancer." (PMID 39474113, 2024). "Meanwhile, PTK7 has a higher expression level in aggressive prostate cancer, suggesting that it may be related to cancer aggressiveness." (PMID 39474113, 2024). "Clinicopathologic variables and PTK7 expression in 180 prostate cancer patients." (PMID 24987951, 2014). "Protein tyrosine kinase 7 (PTK7) has been studied in various tumors, but its role in prostate cancer remains unknown." (PMID 24987951, 2014). "PTK7 expression was evaluated by real-time reverse transcription polymerase chain reaction (RT-PCR) and Western blot analysis in 20 pairs of benign prostatic hyperplasia specimens and prostate cancer specimens." (PMID 24987951, 2014). "Moreover, only PTK7 mRNA levels were upregulated in more than one prostate cancer dataset." (PMID 29717114, 2018). "However, the biological significance of PTK7 in human prostate cancer and lymph node involvement has not been investigated so far." (PMID 24987951, 2014). "The results show that PTK7 may be used as a potential tissue biomarker to avoid overtreatment of non-aggressive prostate cancer." (PMID 24987951, 2014). "FZD4, FZD8, and PTK7, but not FZD2, were more highly expressed in prostate cancer than in benign or normal prostate tissue." (PMID 29717114, 2018).
craniorachischisis (6 papers, 2010 to 2022). Craniorachischisis is the most severe form of neural tube defect in which both the brain and spinal cord remain open to varying degrees. "Following breeding of chuzhoi to congenicity, all phenotypically abnormal embryos (n = 76, E10.5 or older) genotype as homozygous mutant for Ptk7, supporting this mutation as being causative for the craniorachischisis phenotype." (PMID 20704721, 2010). "Several mouse mutants with craniorachischisis exhibit an abnormal, broadened morphology of the ventral midline of the neural plate at the stage and site of closure 1, as seen in Vangl2Lp/Lp, ScribCrc/Crc, Celsr1Crsh/Crsh (unpublished data) mutants and the Ptk7 gene trap allele." (PMID 20704721, 2010). "Craniorachischisis is associated with defective convergent extension and has been mainly found in mice with mutant PCP signaling genes, such as Ptk7 and the Vangl, Celsr, Dvl and Fzd families." (PMID 35514236, 2022). "Homozygous Ptk7 deleterious variants in the mouse disrupted normal NTC, resulting in embryos with craniorachischisis; while fetuses that were doubly heterozygous for Ptk7 and Vangl2 presented with spina bifida." (PMID 30689296, 2019). "A similarly low percentage of Vangl2/PTK7 double heterozygotes exhibit craniorachischisis but nevertheless, there is ample evidence that PTK7 makes an important contribution to the PCP signaling pathway." (PMID 24852369, 2014). "Mutants deficient in the PCP signaling gene Ptk7 exhibit the severest NTD, craniorachischisis." (PMID 35514236, 2022). "However, this hypothesis might also predict that Ptk7;Vangl2 double heterozygotes should have a higher craniorachischisis frequency than Ptk7 homozygotes, whereas we and others have observed the opposite." (PMID 25128525, 2014). "Mouse models indicate that the homogenous disruption of the Ptk7 gene, a PCP regulator, results in craniorachischisis; while embryos that are doubly heterozygous for Ptk7XST87 and Vangl2Lp mutations present with spina bifida." (PMID 30689296, 2019). "Other craniorachischisis mutants exhibit PCP phenotypes (e.g. in the inner ear), although the biochemical role of the protein in PCP signaling is unclear (e.g. Scrib, Ptk7)." (PMID 25128525, 2014).
glioblastoma (6 papers, 2014 to 2025). The most malignant astrocytic tumor (WHO grade IV). "PTK7 has thus been identified as a positive allosteric modulator of GPR133 signaling in glioblastoma." (PMID 39474113, 2024). "As in most solid tumors, in oral squamous cell carcinoma and glioblastoma, PTK7 expression also implies poor OS." (PMID 39474113, 2024). "Meanwhile, knockdown of either GPR133 or PTK7 impairs glioblastoma tumorsphere formation." (PMID 39474113, 2024). "Knockdown of PTK7 impairs glioblastoma tumorsphere formation." (PMID 39474113, 2024). "Furthermore, a recent study found that PTK7 is a GPR133-binding protein in glioblastoma." (PMID 39474113, 2024). "In GBM cells, Id1 is also a potential downstream effector of protein tyrosine kinase 7(PTK7) and transglutaminase 2 (TGM2) which are highly expressed in CD44-high glioblastoma and predicts unfavorable prognosis." (PMID 32410828, 2020). "In glioma, PTK7 was highly expressed in tumor tissues compared to nontumor brain tissues, especially in glioblastoma multiforme (GMB) tissues." (PMID 39474113, 2024). "Interestingly, the pseudokinase RTKs PTK7, ROR1, and ROR2 that activate the Wnt pathway rather than the canonical MAPK and PI3K pathways were mildly to moderately overexpressed in all glioblastoma subgroups." (PMID 34572759, 2021).
intrahepatic cholangiocarcinoma (6 papers, 2014 to 2024). A carcinoma that arises from the intrahepatic bile duct epithelium in any site of the intrahepatic biliary tree. "Previously, we have found that PTK7 was associated with a poor prognosis in patients with intrahepatic cholangiocarcinoma using cDNA mediated annealing, selection, extension and ligation CHiP study (unpublished data)." (PMID 24587299, 2014). "Overexpression of PTK7 has been found in multiple cancers and has been proposed to serve as a prognostic marker for intrahepatic cholangiocarcinoma." (PMID 28545451, 2017). "Overexpression of PTK7 has been found in colon cancer, lung cancer, gastric cancer, acute myeloid leukemia, and intrahepatic cholangiocarcinoma." (PMID 28545451, 2017). "More importantly, intrahepatic cholangiocarcinoma patients with low PTK7 levels had longer disease-free and overall survivals than those with high PTK7 levels, suggesting it may serve as a prognostic predictor." (PMID 28545451, 2017). "In another major type of primary liver cancer, intrahepatic cholangiocarcinoma (ICC), PTK7 was also upregulated." (PMID 39474113, 2024). "PTK7 is one of the coreceptors of the noncanonical Wnt/planar cell polarity signaling pathway, and a previous report shows its strong involvement in the invasion of intrahepatic cholangiocarcinoma." (PMID 35257502, 2022).
cervical carcinoma (5 papers, 2020 to 2025). A carcinoma arising from either the exocervical squamous epithelium or the endocervical glandular epithelium. "In a very recent study, investigating the prognostic role of the PTK-7 in 85 patients diagnosed with cervical carcinoma, overexpression of PTK-7 was associated with malignant clinicopathological features, suggesting shorter progression-free survival." (PMID 31820857, 2020). "It is well established that various cancer markers are over expressed at the cancer cell membranes, for example protein tyrosine kinase 7 (PTK7) in HeLa cells isolated from cervical cancer." (PMID 33494545, 2021).